CXCR3 (C-X-C motif chemokine receptor 3)
Diseases named in the same sentence as CXCR3 in open-access papers (continued):
Sharing a sentence is not in itself a finding about the gene and the disease.
malaria (26 papers, 2009 to 2024). Malaria is a serious and sometimes fatal disease caused by a parasite that commonly infects a certain type of mosquito which feeds on humans. "By contrast, increases in CXCR3+ cTfh have been implicated in the poor development of humoral immunity against malaria and are proportionally increased in patients with primary immunodeficiencies." (PMID 30090099, 2018). "Finally, we investigated the in vivo role of CXCR3 to immunity to blood-stage malaria by determining the course and outcome of P. chabaudi AS infection in wild-type (WT) B6 compared to CXCR3-deficient mice." (PMID 30915078, 2019). "Notably, we detected a decrease in expression of CXCR3 in atMBCs, despite reports that this marker is increased on malaria-associated atMBCs and similar cells in the tonsil and in individuals with HIV, SLE, and CVID." (PMID 25993340, 2015). "Consistent with the emergence of Tr1 cells from Th1 subsets, the majority of Tr1 cells where Th1-like (CXCR3+/CCR6-/CXCR5-/FoxP3-) at day 0 during malaria (median 65.4%, IQR 62.5-73.8%)." (PMID 37968278, 2023). "In a study with P. berghei, pro-inflammatory conditions during severe malaria stunted Tfh cell development by inducing expression of Tbet and CXCR3 on Tfh cells." (PMID 36845571, 2021). "In experimental malaria, coinfection with the chikungunya arbovirus also prevented ECM but through a distinct mechanism involving the IFN-γ-mediated retention of CXCR3-expressing pathogenic CD8+ T cells in the spleen." (PMID 32265335, 2020). "To investigate the in vivo contribution of CXCR3 to control of acute blood-stage malaria, we compared the course and outcome of P. chabaudi AS infection in wild-type (WT) B6 and CXCR3-deficient mice." (PMID 30915078, 2019). "To address the in vivo role of CXCR3 during blood-stage malaria, we compared the course and outcome of P. chabaudi AS infection in WT (B6) and CXCR3-deficient mice." (PMID 30915078, 2019). "To understand the relationship between T-bet and CXCR3 expression during blood-stage malaria, we determined if these markers are co-expressed by CD4+ T cell populations in the spleen." (PMID 30915078, 2019). "Frequencies of CXCR3+CCR6− TFH1s increase transiently but significantly during acute malaria, while CXCR3−CCR6− TFH2 frequencies decrease long-term in response to multiple malaria parasite exposures." (PMID 31156642, 2019). "In malaria-exposed children we found that T-bethi B cells express markers that are known to be associated with atypical MBCs (FCRL5, FCGR2B, CD11c, CXCR3 and CD95)." (PMID 28953967, 2017). "In that context, we postulated that the increased number of splenic IFN-γ-producing T cells observed during malaria when IP-10 mediated chemotaxis was impaired reflected a retention of CXCR3+ T cells in spleens of infected animals." (PMID 19343215, 2009). "However, cTfh cell activation was restricted to Th1-cTfh subsets (CXCR3+) both in vivo during malaria, and in vitro following P. falciparum parasite stimulation of peripheral blood mononuclear cells (PBMCs) from exposed children." (PMID 36845571, 2021). "Furthermore, the significance of the observation of increased CXCR3 expression on splenic CD4+ T cells during malaria was unclear." (PMID 30915078, 2019). "Together, our findings indicate Th1-like CD4+T-bet+Foxp3+ Tregs that express CXCR3 are induced during acute blood-stage malaria and suggest CXCR3 expression on CD4+ Th1 cells may contribute to their migration to the spleen." (PMID 30915078, 2019). "Altogether, our findings indicate that CXCR3 expression on effector CD4+T-bet+Foxp3− cells may contribute to the migration of these cells to the spleen during malaria suggesting a role for CXCR3 in immunity to P. chabaudi AS infection." (PMID 30915078, 2019). "To determine whether such flexibility was altered during malaria we evaluated the expression of CXCR3 and CC chemokine receptor 6 (CCR6) by CD4+ T cell populations in P. vivax-infected patients BT and AT." (PMID 28700710, 2017).
malaria (continued). "In a previous study, we found that the majority of NK cells and T cells in brains of malaria-infected mice express CXC chemokine receptor 3 (CXCR3) suggesting that trafficking through this pathway is strongly associated with lymphocyte recruitment leading to cerebral disease." (PMID 19343215, 2009). "Moreover, in an independent experiment (n = 10 Malian children) T-bethi B cells of malaria-exposed children expressed markers that are known to be associated with atypical MBCs, with higher surface expression of FCRL5, CD11c, CXCR3 and CD95, and decreased expression of CD35, CD40, CXCR5 and CCR7." (PMID 28953967, 2017). "Here, we tested whether AT1R expressed in Plasmodium-specific CD8+ T cells modulates the expression of molecules involved in the migration and sequestration of pathogenic CD8+ T cells in inflamed tissues during severe malaria, such as LFA-1 (CD11a), CCR5, and CXCR3." (PMID 28261571, 2017). "Previous studies show an increase of both CXCR3+ cTh1 and CXCR3+CCR6- cTfh1 phenotypes in P. falciparum-infected children residing in areas of high malaria transmission." (PMID 39475899, 2024). "Anti-CXCR3-mediated depletion of liver Trm cells completely abrogates the protection induced by RAS and prime-trap malaria vaccination." (PMID 37056783, 2023). "In favor of this, a lower expression of CXCR3 along with an augmented BCL6 and PD-1 expression in the present study, possibly suggest the increased population of TFH cell following malaria pathology." (PMID 31614626, 2019). "The relative involvement of the 3 CXCR3 chemokines (CXCL9, CXCL10 and CXCL11) in the recruitment of inflammatory leucocytes to the brain of malaria-infected mice has been extensively investigated." (PMID 24476686, 2014). "Our data indicate that Heme/HO-1, CXCL10/CXCR3 and STAT3 molecules as well as related signaling pathways play very important roles in the pathogenesis of severe malaria." (PMID 22479586, 2012). "Taken together, our data indicate that Heme/HO-1, CXCL10/CXCR3 and STAT3 molecules as well as related signaling pathways play very important roles in inflammation and organ damage in the pathogenesis of severe malaria." (PMID 22479586, 2012). "Interestingly, however, while CXCR3+TFH are affiliated with neutralizing antibodies in HCV and Zika virus infection, they appear to lead to poor prognosis in malaria." (PMID 35619703, 2022). "Previous studies demonstrated CXCR3 is expressed on CD4+ T cells in the spleen during malaria, but the phenotype was not defined." (PMID 30915078, 2019). "The present study shows the subordinate expression pattern of chemokine receptors CXCR3 and CCR8 in response to increased malaria burden, it exemplifies the reduced trafficking of TH1, CD8+T cells, NK cells, monocytes and TH2 cells within lymphoid organ or in the peripheral tissues." (PMID 31614626, 2019). "RpMΦs may produce CXCR3- and/or CCR5-binding chemokines by a mechanism similar to that observed during early Candida infection – CXCR3 and CCR5 are the main upregulated chemokine receptors in splenic CD4+ T cells during acute blood-stage malaria." (PMID 26441984, 2015). "Analysis of chemokine receptor usage of brain-infiltrating T cells showed that the majority of αβT cells present in brain blood vessels of malaria-infected control mice expressed CXCR3 but not CCR5." (PMID 19343215, 2009). "Since CXCR3 and CCR6 are tissue homing receptors, especially for the liver, these cells may have been directed to the liver considering the liver-tropism of malaria SPZ." (PMID 35062785, 2022). "Previous studies showed that CXCR3 expression increases on CD4+ and CD8+ T cells in the spleen during P. berghei ANKA infection suggesting this chemokine receptor may be important in T cell trafficking to the spleen during malaria." (PMID 30915078, 2019).
malaria (continued). "CD8+ T cells isolated from the spleen and brain of malaria-infected mice significantly upregulated CCR5, CCR2, CXCR4 and CXCR3 expression, initially suggesting that trafficking via these chemokine receptors could be involved in the recruitment of inflammatory cells during severe disease." (PMID 24476686, 2014). "The role of CXCR3 chemokines in malaria has not been extensively investigated." (PMID 19343215, 2009). "Thus, in the absence of IP-10-dependent trafficking, CXCR3+ T cells accumulate in spleens of malaria-infected animals." (PMID 19343215, 2009). "However, neither the role of CXCR3 expression on T cells in the spleen during malaria nor the phenotype of the T cells, especially of CD4+ T cells, expressing this chemokine receptor have been investigated in mice infected with P. berghei ANKA or in other rodent malaria models." (PMID 30915078, 2019).
psoriasis (26 papers, 2009 to 2025). An autoimmune condition characterized by red, well-delineated plaques with silvery scales that are usually on the extensor surfaces and scalp. "Recurrent psoriasis-like condition in mice also induced increased activation of memory T cells, augmented frequencies of CXCR3+4-1BB+ and PD-1+TIM-3+ CD4+ T cells as well as CD8+ T cells with a highly differentiated phenotype." (PMID 40599782, 2025). "In conclusion, these results hint at possible differences in the expression of receptors associated with tissue homing in CD8 T cells, namely CXCR3 and CCR4, from patients with mild-to-moderate psoriasis compared to healthy controls." (PMID 40391222, 2025). "CXCL10 and CXCR3 were found in keratinocytes and dermal infiltrates from active psoriasis plaques, and psoriasis patients had higher serum levels of CXCL1052." (PMID 38321132, 2024). "Chemokine CXCR3 was elevated in psoriasis both in M1 and M2, with values six times higher in the first." (PMID 36677041, 2023). "In general, the percentage of Th17, CXCR3+-Th17, Th17.1, and Th1 was significantly decreased in responding to therapy psoriasis patients following treatment compared to baseline." (PMID 35925616, 2022). "Using multiparameter flow cytometry we examined T-cell subpopulations characterized by CCR6, CCR4, and CXCR3 chemokine receptor surface expression at baseline and after initiation of biologic therapy in PBMCs collected from 30 psoriasis patients." (PMID 35925616, 2022). "In psoriasis patients receiving biologic IL-17 therapeutic blockade circulating Th1, Th17 and sub-populations as CXCR3+-Th17 and Th17.1 were decreased as early as 3 months after treatment initiation." (PMID 35925616, 2022). "The percentage of CCR6+CXCR3− cells within the CD4+ TEM subset in the total cohort of psoriasis and PsA patients significantly correlated with serum concentration of CRP." (PMID 31350460, 2019). "Recruitment of CXCR3+ immune cells can aid in the response to skin infection while also enhancing autoimmune conditions such as psoriasis." (PMID 30320116, 2018). "The observation that CXCR3+ LFA-1+ T cells increased systemically in psoriasis-like conditions indicates that chronic skin inflammation may induce T cells with enhanced migratory capacity." (PMID 40599782, 2025). "Therefore, increased CXCR3 expression on T cells within the spleens in recurrent psoriasis-like conditions provides an important mechanistic insight." (PMID 40599782, 2025). "Notably, in the CD4+ T cell compartment, the activation marker 4-1BB was upregulated on inflammatory CXCR3+CD4+ T cells in all memory subsets in psoriasis-like conditions compared to the control group, with a more pronounced increase in CD4+ TCM and TTE cells." (PMID 40599782, 2025). "In a study conducted in patients with psoriasis and atopic dermatitis, reductions of CD56bright NK cells were connected with the previous findings of accumulated CXCR3 expressing CD56bright NK cells in lesional skin, probably due to CXCL10 production by psoriatic keratinocytes." (PMID 37744329, 2023). "Recent study indicated that CCR4 and CXCR3 may participate in psoriasis recurrence or redistribution to distant sites." (PMID 34012433, 2021). "However, the comparison of the phenotype of circulating CD8+ T cells between psoriasis patients and healthy subjects evidenced a significant increase in the percentage of CCR4+CXCR3+ CD8+ TCM cells in the circulation of psoriasis patients." (PMID 32318062, 2020). "Furthermore, the Th1 polarizing key transcription factor T-bet, Th1 effector cytokine IFN-γ, and Th1 type chemokine receptor CXCR3 were also expressed at a higher level in both acne and psoriasis lesions, indicating the involvement of Th1 effector cells." (PMID 25153527, 2014). "Thus, we compared expression of T cell, B cell, and macrophage markers and their associated proteins, TIA-1, CXCR3, and CXCL10 in DLE lesional skin, psoriasis lesional skin, and normal skin." (PMID 24744689, 2014).
psoriasis (continued). "However, patients showed an expanded circulating population of CD8+ TCM cells with phenotype CCR4+CXCR3+ that could play a role in the pathophysiology of psoriasis and possibly in disease recurrence." (PMID 32318062, 2020). "Interestingly, a reduced number of CXCR3-expressing T cells has previously been shown in the peripheral blood of patients with psoriasis, which had been speculated to be due to recruitment of these cells into skin lesions." (PMID 32958743, 2020). "We also found that circulating CXCR3+CD8- MAIT cells in psoriasis negatively correlate with PASI scores, hinting at the possible recruitment of CD8- MAIT cells expressing the trafficking receptor CXCR3 from the circulation to inflamed skin in mild disease." (PMID 40391222, 2025). "CXCR3 expression was strongly upregulated on TCM, TEM and terminal effector CD4+ T cells in the recurrent psoriasis-like group." (PMID 40599782, 2025). "CXCR3 expression was, instead, reduced in CD8 and CD8 memory T cell compartments in psoriasis compared to healthy controls." (PMID 40391222, 2025). "As MAIT cells display an EM-like phenotype, a similar correlation between circulating CXCR3+CD4+ EM T cells and PASI scores was observed in patients with psoriasis." (PMID 40391222, 2025). "Increased CD3+CD4+CXCR3+, CD3+CD4+CCR6+CCR4+CXCR3+(CXCR3+-Th17), and CD3+CD4+CCR6+CCR4-CXCR3+(Th17.1) cell populations were observed in patients with psoriasis in comparison to healthy individuals (n = 10)." (PMID 35925616, 2022). "The mean percentages of inflammatory cells from psoriasis skin lesions expressing CXCL9, CXCL10, CXCL11 and CXCR3 were 3.0% ± 3.4%, 3.0% ± 2%, 46.8% ± 17.7% and 21.2% ± 19.5%, respectively." (PMID 28436448, 2017). "These periadnexal areas also contained higher expression of TIA-1, CXCR3, and CXCL10 in DLE versus psoriasis lesional skin." (PMID 24744689, 2014). "CXCR3, CXCL10, and TIA-1 were elevated in periadnexal sites of DLE lesional skin versus psoriasis lesional skin." (PMID 24744689, 2014). "CXCL10 and CXCR3, which were both up-regulated in the periadnexal areas of DLE versus psoriasis lesional skin, appeared to mimic the expression patterns of effector T cells and macrophages." (PMID 24744689, 2014). "By contrast, the 4-1BB+ cells were not increased on CXCR3+ CD8+ T cells in psoriasis-like conditions." (PMID 40599782, 2025). "IL-17 therapeutic blockade decreased CD3+CD4+CCR6+, CD3+CD4+CXCR3+, CD3+CD4+CCR6-CXCR3+(Th1), CD3+CD4+CCR6+CCR4+(Th17), CD3+CD4+CCR6+CCR4+CXCR3+(CXCR3+-Th17), and CD3+CD4+CCR6+CCR4-CXCR3+(Th17.1) cell populations in responding psoriasis patients." (PMID 35925616, 2022). "Psoriasis patients without arthralgia had lower numbers of CCR6-CCR4+CXCR3+ memory Th cells and higher numbers of CCR6+CCR4-CXCR3-memory Th cells compared to HC." (PMID 35045868, 2022). "One CXCR3 antagonist, AMG 487, has been studied in psoriasis and graft vs. host disease." (PMID 34682144, 2021). "In immunopathological skin conditions such as psoriasis, the expanded subset of TCM cells expressing CCR4 and CXCR3 could play a role in disease recurrence or redistribution to distant sites such as joint synovial tissues and enthesis." (PMID 32318062, 2020). "While CXCR3+ cells may play a role in psoriasis, this is not the only chemokine receptor associated with disease as one study showed that intraepidermal T cells expressing CLA, CCR4 and CCR6 were more prevalent than CXCR3+ T cells." (PMID 30320116, 2018).